VDR (vitamin D receptor)
Diseases named in the same sentence as VDR in open-access papers (continued):
Sharing a sentence is not in itself a finding about the gene and the disease.
pneumonia (5 papers, 2021 to 2026). An acute, acute and chronic, or chronic inflammation focally or diffusely affecting the lung parenchyma, caused by an infection in one or both of the lungs (by bacteria, viruses, fungi, or mycoplasma.). "We aimed to investigate the association between two vitamin D receptor (VDR) gene polymorphisms, FokI and TaqI, and susceptibility to complicated pneumonia in Egyptian children compared to uncomplicated pneumonia." (PMID 37559014, 2023). "In this work, our objective was to study association between VDR polymorphisms, namely FokI and TaqI, and susceptibility to complicated pneumonia in Egyptian children compared to those with uncomplicated CAP." (PMID 37559014, 2023). "As far as we know, this study is unique in elucidating relationship between occurrence of local pneumonia complications and two VDR polymorphisms, namely FokI and TaqI." (PMID 37559014, 2023). "Our findings pointed out that FokI, but not TaqI, SNP in the VDR gene could be a genetic risk factor for progression to complicated pneumonia in Egyptian children." (PMID 37559014, 2023). "This work showed that VDR gene TaqI SNP could not be a risk factor for pneumonia or local pneumonia complications in Egyptian children." (PMID 37559014, 2023). "Then, the expressions of 25-OH-VD, VDR, TGFβ, IL-2, IFN-γ, TNFα, IL-1β, Ca2+, PCT, CRP, and IL-6 in mild pneumonia, severe pneumonia, and healthy controls were determined using qRT-PCR, western blot, ELISA, and calcium colorimetry assay." (PMID 34643152, 2021). "The expression of vitamin D receptor (VDR) was down-regulated, while the transforming growth factor β (TGFβ), nuclear YAP, and TAZ were up-regulated in the peripheral blood mononuclear cells (PBMCs) of neonates with severe pneumonia." (PMID 34643152, 2021).
thyroid (5 papers, 2016 to 2025). "While these findings enhance our understanding of VDR expression patterns in thyroid lesions, their potential diagnostic utility requires further investigation with the inclusion of control tissues." (PMID 40008182, 2025). "The study’s objective was to investigate the association between VDR gene polymorphism (rs2228570) with blood serum levels of 25-OH vitamin D in patients with thyroid pathology from western Ukraine." (PMID 34621381, 2021). "In thyroid diseases, out of the VD pathway SNP's in the VDR are the best-studied genetic associations with HT and DTC." (PMID 30271381, 2018). "Surprisingly, in our study all samples showed positive for VDR staining because colloid nodule is one of the thyroid disorders and it is a benign thyroid lesion." (PMID 40008182, 2025). "In the current study, the higher expression of VDR in the colloid nodule with worse condition of larger and multinodules adds another line of evidence for the role of vitamin D in thyroid diseases." (PMID 40008182, 2025). "Future studies may further explore the potential of VDR expression as a prognostic marker for colloid nodule progression and the potential of vitamin D supplementation in preventing and managing thyroid diseases." (PMID 40008182, 2025). "Concerning VDR polymorphisms, previous studies did not evaluate the relationship with thyroid auto antibodies." (PMID 27011770, 2016).
Ureteral obstruction (5 papers, 2016 to 2024). Obstruction of the flow of urine through the ureter. "It has been confirmed that VDR loss occurs in the early stage of unilateral ureteral obstruction model in mice and early renal biopsy in patients (including patients with minimal change nephropathy, DN, and hypertensive nephropathy)." (PMID 37991543, 2024).
vulvar cancer (5 papers, 2017 to 2025). "More studies will need to focus on the VDR and its influence on endometrial, ovarian, cervical, vaginal and vulvar cancer." (PMID 29113037, 2017). "The same year another study focused on the VDR expression in vulvar cancer." (PMID 29113037, 2017).
abortion (4 papers, 2017 to 2024). the ending of pregnancy by removing a fetus or embryo before it can survive outside the uterus. "Women with recurrent pregnancy loss (RPL) have lower VDR placental and serum expression compared to normal pregnant women; decreased VDR expression in the first trimester of pregnancy is likely associated with RPL indicating an abnormal immune mechanism." (PMID 37346332, 2023). "As a result, it seems that altered metabolism of the VD/VDR complex via immune response modulation might be significant in the pathogenesis of both spontaneous abortion and RM." (PMID 38816754, 2024). "A few years ago it was shown that disturbed metabolism of the vitamin D/receptor (VD/VDR) complex may be important in the etiology of spontaneous abortion, as well as in the etiology of recurrent miscarriages (RM)." (PMID 33633340, 2021).
acromegaly (4 papers, 2015 to 2023). Acromegaly is an acquired disorder related to excessive production of growth hormone (GH) and characterized by progressive somatic disfigurement (mainly involving the face and extremities) and systemic manifestations. "They showed the VDR FokI ff genotype was associated with a decreased risk, while FokI Ff genotype was associated with a significantly increased risk of acromegaly." (PMID 37446150, 2023). "The aim of the study was to assess possible roles of VDR gene polymorphisms in acromegaly, with regard to the activity of the disease in comparison to controls." (PMID 31616375, 2019). "In one previous study, it was found that the VDR FokI ff genotype was associated with a decreased risk and FokI Ff genotype with a significantly increased risk for acromegaly." (PMID 31616375, 2019). "The primary objective of this study was assessment of possible roles of VDR gene polymorphisms in acromegaly, with regard to the activity of the disease and compared them with a control group." (PMID 31616375, 2019). "In conclusion these findings suggest a possible role of VDR FokI polymorphism in the risk of acromegaly." (PMID 25839036, 2015). "In this study we found that, while the VDR FokI ff genotype was associated with a decreased risk, FokI Ff genotype was associated with a significantly increased risk of acromegaly." (PMID 25839036, 2015). "In the present study we aimed to investigate possible associations of vitamin D receptor polymorphisms and VDR activity levels with acromegaly and acromegaly disease characteristics." (PMID 25839036, 2015). "VDR FokI ff genotype was significantly decreased in acromegaly patients (P = 0.035) and carriers of FokI Ff genotype had a 1.5-fold increased risk for acromegaly (OR: 1.5, 95% CI: 1.07–2.1; P = 0.020)." (PMID 25839036, 2015). "We examined three genetic variants of the VDR in acromegaly patients." (PMID 25839036, 2015). "Our study suggests that VDR FokI genotypes might affect the development of acromegaly and VDR polymorphisms may play a role in the course of acromegaly as a consequence of altering hormonal status." (PMID 25839036, 2015). "Distribution of vitamin D receptor genotypes and minor allele frequency (MAF) in acromegaly and control group." (PMID 31616375, 2019). "VDR genotypes can play a role as a consequence of altering hormonal status in the course of acromegaly." (PMID 25839036, 2015). "We aimed to investigate possible associations between vitamin D receptor (VDR) polymorphisms and acromegaly." (PMID 25839036, 2015). "VDR FokI ff genotype was significantly decreased in acromegaly patients (9.6%) compared to controls (24.1%) (OR: 0.4, 95% CI: 0.16–0.99; P = 0.035)." (PMID 25839036, 2015). "What is more, tt (TaqI), aa (ApaI), and bb (BsmI) genotypes of VDR gene may be associated with better bone quality and microarchitecture (higher TBS), which may lead to a lower risk of osteoporotic fractures in acromegaly patients." (PMID 31616375, 2019). "While the function of the RXRs in tumorigenesis has not been studied as thoroughly as that of VDR, RXRs have been implicated in the tumorigenesis of somatotroph adenomas." (PMID 25839036, 2015). "Genotype distributions for VDR ApaI, TaqI, BsmI, and FokI polymorphisms did not deviate significantly from HWE in acromegaly group as well as in control group (p > 0.05)." (PMID 31616375, 2019).
Addison’s disease (4 papers, 2011 to 2022). "It was therefore concluded that the VDR genotype was linked to Addison’s disease." (PMID 36313775, 2022).
adrenocortical carcinoma (4 papers, 2015 to 2025). "Patients with adrenocortical carcinoma were found to have higher methylation of cytosine nucleotide of CpG islands in VDR promoter in adrenal glands, leading to reduction of VDR protein and loss of its protective role against malignant growth." (PMID 36246903, 2022). "We showed a decreased expression of VDR mRNA and protein in a small group of human adrenocortical carcinomas (ACCs), suggesting the loss of a protective role of VDR against malignant cell growth, as suggested for other cancer types." (PMID 26843863, 2015). "We previously showed a decreased expression of vitamin D receptor (VDR) mRNA/protein in a small group of adrenocortical carcinoma (ACC) tissues, suggesting the loss of a protective role of VDR against malignant cell growth in this cancer type." (PMID 26843863, 2015). "Research has shown increased cytosine nucleotide methylation in the CpG island of the adrenal VDR promoter in patients with adrenal cortical carcinoma, resulting in diminished protective effects of the VDR protein against malignant tumors." (PMID 40290121, 2025). "The reduced-absent expression of VDR mRNA and protein in adrenocortical cancer may be caused by different molecular mechanism." (PMID 26843863, 2015). "Moreover, methylation of VDR promoter has not been specifically reported in all genome-wide methylation studies on adrenocortical cancer." (PMID 26843863, 2015). "In this regard, the human adrenocortical carcinoma H295R cell line, which provides the most appropriate model for ACC study, does not have VDR gene methylation (personal observation)." (PMID 26843863, 2015).
ankylosing spondylitis (4 papers, 2022 to 2026). An autoimmune chronic inflammatory disorder characterized by inflammation in the vertebral joints of the spine and sacroiliac joints. "Two H19-dependent regulatory axes together affect the expression of VDR and increase the inflammatory response in Ankylosing Spondylitis (AS)." (PMID 38475720, 2024). "Further statistical analysis revealed some noteworthy relations between the Bath Ankylosing Spondylitis Disease Activity Index (BASDAI) and the studied VDR polymorphisms." (PMID 36292758, 2022).
benign prostatic hyperplasia (4 papers, 2003 to 2024). A non-cancerous nodular enlargement of the prostate gland. "The use of vitamin D analogues specific to the VDR in human prostatic tissue has resulted in a significant shrinkage of the enlarged gland in men with benign prostatic hyperplasia." (PMID 34015193, 2021).
cardiomyopathy (4 papers, 2017 to 2023). A disease of the heart muscle or myocardium proper. "Additionally, vitamin D receptor (VDR) polymorphism and expression have also been used as potential risk factors for cardiovascular diseases such as cardiomyopathy and HF." (PMID 34070202, 2021). "CKD also induces erythropoietin deficiency, decreased vitamin D receptor activation, and fluid acumination, which might affect cardiac function through cardiomyopathy." (PMID 28264675, 2017). "Vitamin D deficiency is also correlated with cardiac steatosis, and VDR gene knockout mice display increased interstitial fibrosis with overexpression of collagen (1α1, 3α1) and matrix metalloproteinase (MMP-2), leading to cardiomyopathy and HF." (PMID 34070202, 2021). "Additionally, it has been demonstrated that Sirt-1 can improve diabetes-related cardiomyopathy by activating AMPK and PGC1-a, which may also be influenced by the activation of the vitamin D receptor." (PMID 37764807, 2023).
celiac disease (4 papers, 2017 to 2022). An autoimmune genetic disorder with an unknown pattern of inheritance that primarily affects the digestive tract. "Neither were genetic variants at the vitamin D receptor gene associated with later celiac disease." (PMID 28686601, 2017).
cholangiocarcinoma (4 papers, 2017 to 2025). A carcinoma that arises from the intrahepatic biliary tree (intrahepatic cholangiocarcinoma) or from the junction, or adjacent to the junction, of the right and left hepatic ducts (hilar cholangiocarcinoma). "VDR, the exclusive mediator of 1,25(OH)2D effects, exhibits increased expression during cancer development in cholangiocarcinoma cells." (PMID 39749730, 2025). "Similar results were found in a single study looking at the impact of VDR expression in cholangiocarcinoma in a Thai study of 111 patients." (PMID 30344947, 2018). "VDR expression was also found in human cholangiocarcinoma (CCA) tissue specimens." (PMID 35505652, 2022). "Furthermore, vitamin D/VDR signaling is involved in regulating the expression of lipocalin 2 (LCN2), an oncogene highly expressed in human intrahepatic cholangiocarcinoma tissue." (PMID 35505652, 2022).
diffuse large B-cell lymphoma (4 papers, 2012 to 2026). "Most VDR mutations are concentrated in diffuse large B-cell lymphoma, with an amplification frequency of 4% and a deep deletion frequency of 2.2%." (PMID 39268267, 2024). "However, the study did find certain Bsml and TaqI alleles to be associated with increased risk for diffuse large B-cell lymphoma and a FokI allele to be related to increased risk for T cell lymphoma, possibly due to decreased transactivation of VDR." (PMID 35053549, 2022). "In diffuse large B-Cell lymphoma derived cell lines, treatment with vitamin D3 and a selective VDR-agonist reduced cell growth whereas again observed VDR expression was low." (PMID 22672495, 2012).
eczema (4 papers, 2015 to 2022). "A vitamin D-related SNP on CYP27A1 was also found to be protective against eczema, whereas CYP2R1 and VDR haplotypes appear to alter eczema susceptibility." (PMID 28486474, 2017). "Furthermore two CYP2R1 haplotypes increased eczema risk whereas one vitamin D receptor haplotype lowered eczema risk." (PMID 26239464, 2015). "Studies also found that VDR agonists can regulate the aberrant immune resposnes; such as improving the allergen-triggered eczema in mice; modulating B cell activities to suppress the production of IgE and suppressing the Th17 cell polarization-related nephritis." (PMID 28881831, 2017).
extrapulmonary tuberculosis (4 papers, 2010 to 2019). A tuberculosis that occurs at body sites other than the lung. "One study found that among Gujarati Asians living in London, the f allele of the Fok1 locus of the vitamin D receptor gene was associated with extrapulmonary tuberculosis." (PMID 20096113, 2010). "In this pilot study among extrapulmonary tuberculosis patients with well-characterized immune defects, genetic variants in IL-1β, VDR Fok1, and TLR2 were associated with an increased risk of extrapulmonary disease." (PMID 20196868, 2010). "The results of this study suggest that an evaluation of the underlying mechanism(s) of the genetic variants in IL-1β +3953, VDR Fok1 A/G, and the TLR2 microsatellite--and their role in the pathogenesis of extrapulmonary tuberculosis--is warranted." (PMID 20196868, 2010). "Our results are consistent with the previously noted association between IL-1β +3953 and tuberculous pleurisy, and VDR Fok1 and several forms of extrapulmonary tuberculosis--both noted among in Gujarati Asians living in London." (PMID 20196868, 2010).
fibromyalgia (4 papers, 2022 to 2025). A chronic disorder of unknown etiology characterized by pain, stiffness, and tenderness in the muscles of neck, shoulders, back, hips, arms, and legs. "A study published in 2022 revealed that the homozygous genotypes of the VDR ApaI and wild-type FokI variants were linked to muscle pain and weakness in patients with fibromyalgia." (PMID 38138892, 2023). "Vitamin D receptor (VDR) has been proposed as a possible marker for fibromyalgia syndrome (FMS)." (PMID 36000140, 2022).
gastritis (4 papers, 2016 to 2023). Inflammation of the stomach. "Compare the VDR expression in gastritis, IM, and adenocarcinoma between male and female patients." (PMID 34881266, 2021). "VDR expression in the stomach may differ in the areas of gastritis, IM, and gastric adenocarcinoma." (PMID 34881266, 2021). "There was no statistical difference of mean VDR expression between male and female patients in the gastritis (42.2 ± 25.0 vs. 48.9 ± 27.7, P = 0.58), IM (41.8 ± 17.3 vs. 41.7 ± 14.7, P = 0.73), and adenocarcinoma (36.6 ± 18.8 vs. 36.6 ± 18.5, P = 0.98)." (PMID 34881266, 2021). "The mean expressions of VDR, Ki67, and CK18 among gastritis, IM and cancer." (PMID 34881266, 2021). "There was no information about gastritis, malignancy, H pylori virulence, and stomach vitamin D receptor status." (PMID 27149497, 2016). "However, mean values of VDR expression were no statistical difference among gastritis, IM, and adenocarcinoma by ANOVA (P = 0.404)." (PMID 34881266, 2021). "When a correlation analysis between VDR and Ki67 or CK18 was performed, VDR expression was not correlated with Ki67 or CK18 expression in gastritis, IM and adenocarcinoma site." (PMID 34881266, 2021).